FBXO36 (F-box protein 36)
Description:
Substrate-recognition component of the SCF (SKP1-CUL1-F-box protein)-type E3 ubiquitin ligase complex.
Synonyms: FBX36; FLJ37592
Tractability: No criterion of Open Targets' tractability assessment is met for any kind of drug.
Gene: Protein-coding gene on chromosome 2 (229,922,302 to 230,013,119, forward strand). Ensembl gene ENSG00000153832.
Subcellular location (Human Protein Atlas): Nucleoli; Nucleoplasm
Gene Ontology:
Biological process: SCF-dependent proteasomal ubiquitin-dependent protein catabolic process
Cellular component: SCF ubiquitin ligase complex
Genetic constraint (gnomAD): Loss-of-function variants: 14 observed, 13.26 expected, observed/expected ratio (o/e) 1.06, 90% interval 0.7 to 1.63. The upper end of that interval is the gene's LOEUF score, 1.63, which puts it in group 6 of 6, group 1 being the genes least tolerant of losing a copy. Missense variants: 196 observed, 201.79 expected, observed/expected ratio (o/e) 0.97, 90% interval 0.86 to 1.09. Synonymous variants: 74 observed, 79.88 expected, observed/expected ratio (o/e) 0.93, 90% interval 0.77 to 1.12.
Homologues: Orthologues: chimpanzee FBXO36 (99% identical), pig FBXO36 (85% identical), macaque FBXO36 (81% identical), rabbit FBXO36 (80% identical), mouse Fbxo36 (76% identical), dog FBXO36 (69% identical), rat Fbxo36 (65% identical), guinea pig FBXO36 (63% identical), tropical clawed frog fbxo36 (59% identical), zebrafish fbxo36b (53% identical), zebrafish fbxo36a (50% identical). Paralogues in human: WDR49 (21% identical), EFCAB8 (19% identical), WDR64 (19% identical), FBXW7 (16% identical), FBXW9 (13% identical), TRAF7 (12% identical), WDR86 (12% identical), BTRC (12% identical), FBXW11 (12% identical), FBXW8 (12% identical), FBXW12 (9% identical), WDR54 (9% identical), and 2 more.